CD68 (CD68 molecule)
Diseases named in the same sentence as CD68 in open-access papers (continued):
Sharing a sentence is not in itself a finding about the gene and the disease.
colorectal cancer (62 papers, 2004 to 2025). A primary or metastatic malignant neoplasm that affects the colon or rectum. "TAM biomarkers, such as CD68, CD163, and TREM2, among others, are associated with clinical outcomes in various solid tumors, whereas CD68 is associated with a good prognosis in colorectal cancer but typically reflects a poor outcome in other cancers." (PMID 41181157, 2025). "In colorectal cancer and hepatocellular carcinoma, B7-H3 tumor expression was associated with a higher infiltration of CD68+ macrophages and the polarization of M1 to M2 macrophages." (PMID 34572755, 2021). "Thus, IHC analysis of Japanese cohort of 30 patients with CRC showed that low levels of CD68+ TAMs in invasive front and tumor stroma were associated with more advanced colorectal cancer, while high amount of TAMs was found in patients with good prognosis." (PMID 33194645, 2020). "The mIHC analyses revealed colocalization of CXCL7 with the macrophage marker CD68 in colorectal cancer clinical samples." (PMID 40368902, 2025). "Unsupervised clustering analysis divided colorectal cancer into three subtypes with distinct prognostic outcomes, and correlation analysis revealed the synergy among B cells, CD68+IDO1+TAMs, and T lineage cells in producing an effective immune response." (PMID 38951801, 2024). "By combining the prognostic information of anti-tumoural CD8+ lymphocytes and tumour supportive CD68+CD163+ macrophages in colorectal cancer we generated a signature of immune activation (SIA)." (PMID 36724681, 2023). "In fact, research has shown that MSI-H colorectal cancer patients with a high abundance of CD68+CD74+ macrophages can benefit significantly from the treatment of nivolumab and pembrolizumab." (PMID 36238279, 2022). "Correlation of high expression of CD68 with favorable prognosis was also demonstrated in colorectal cancer." (PMID 36686729, 2022). "A recent study has consistently shown that the ratio of CD163+/CD68+ macrophages in tumor tissue is an independent prognostic factor for survival in patients with colorectal cancer." (PMID 36860286, 2021). "S100A8/A9 expression was identified in tumor-infiltrating CD68+ macrophages in human colorectal cancer." (PMID 34209679, 2021). "IF staining also indicated the co-localization of OPN and CD68 at the stromal area of tumor sections in patients with colorectal cancer." (PMID 34209679, 2021). "In patients with colorectal cancer treated with chemotherapy plus bevacizumab, low CD68+ TAM infiltration was predictive for high OS." (PMID 34209679, 2021). "Using double immunostaining of colorectal cancer tissues, it was shown that CD68+ TAMs express COX-2 in region with high expression of mucin secreted by tumor cells." (PMID 34209679, 2021). "High numbers of CD68+ TAMs in the invasive front were associated with favorable outcome, while other reports indicated that intratumoral CD68+ TAM counts were related with tumor penetration, lymph node metastasis and advanced stages of colorectal cancer." (PMID 34064974, 2021). "Analysis of 210 samples with primary colorectal cancer (Bulgaria) showed that lower number of CD68+ TAMs in tumor invasive front significantly correlated with the presence of metastases in local lymph nodes, with distant metastases and with more advanced tumor stage (III and IV stages)." (PMID 33194645, 2020). "Correlation analysis of CCL2 and CD68 expression in cohort (n=83) colorectal cancer (CRC) tissues." (PMID 33330033, 2020). "The aim of the study is the assessment of the intensity of the infiltration of tumor-associated macrophages (TAMs) CD68+/iNOS− and Tregs CD8+/FoxP3+ in colorectal cancer (CRC) patients as prognostic factors with respect to disease-free survival (DFS) and overall survival (OS)." (PMID 28343267, 2017).
colorectal cancer (continued). "To determine whether Gas6 is likewise expressed in macrophages within human colorectal cancer tissue, we performed stainings and double immunostainings for Gas6 and the macrophage marker CD68, revealing Gas6 expression in a subpopulation of macrophages." (PMID 27486820, 2016). "The levels of CD68, a macrophage marker, correlated with an adverse prognosis in glioblastoma, kidney renal clear cell carcinoma, hepatocellular carcinoma, lung squamous cell carcinoma, and thyroid carcinoma and a favorable prognosis in colorectal cancer, OS, and kidney chromophobe." (PMID 37279073, 2023). "Therefore, we examined CD68 expression in human colorectal cancer samples." (PMID 34580284, 2021). "Multiplex immunofluorescence (mIF) quantification revealed significantly increased densities of both CD68+CD86+ and CD68+CD163+ TAMs, and a higher CD68+CD163+/CD68+CD86+ ratio in colorectal cancer (CRC) (all P < 0.001)." (PMID 41395618, 2025). "Our SPP1+ TAM population also expressed CD68 but had low expression of CD206 and CD163, which differed slightly from another study of SPP1+ macrophages in colorectal cancer that had high CD206 expression." (PMID 39075108, 2024). "Specimens from 267 colorectal cancer cases were analyzed by immunohistochemistry to determine GSDMB expression, CD3+, CD4+, and CD8+ T lymphocytes, CD20+ B lymphocytes, CD68+ macrophages, and S100A8+ immune cells." (PMID 38711020, 2024). "The TAM markers CD68 and CD163 were analyzed by multiplex fluorescence immunohistochemistry and digital image analysis on tissue microarrays of 1720 primary colorectal cancers." (PMID 38407700, 2024). "We analysed 12,592 tissue microarray (TMA) spots from 3,545 colorectal cancers sourced from more than 240 institutions in two clinical trials (QUASAR 2 and SCOT) stained for CD4, CD8, CD20, CD68, FoxP3, pan‐cytokeratin, and DAPI by mIF." (PMID 37697694, 2023). "We used multiple immunofluorescence techniques to detect the expression of CD19, CD163, C-kit, CD68, NOS2, mast cell tryptase, and CD16 markers in colorectal cancer tissues and surrounding normal tissues on the same slide." (PMID 35646079, 2022). "In contrast, high number of CD68+ stabilin-1+ TAMs correlated with longer DSS and predicted a favorable prognosis in early stage I colorectal cancer (CRC) patients." (PMID 36686729, 2022). "The aim of this study was to validate our previous results regarding the prognostic role of CLEVER-1+ macrophages, CD68+ macrophages, and CLEVER-1+ lymphatic vessels in stage I–IV colorectal cancer." (PMID 34885098, 2021). "Cellular subpopulations within the colorectal tumor microenvironment (TME) include CD3+ and CD8+ lymphocytes, CD68+ and CD163+ macrophages, and tumor buds (TBs), all of which have known prognostic significance in stage II colorectal cancer." (PMID 32435699, 2020). "Here, we profiled macrophages in a series of 150 colorectal cancer (CRC) cases by immunohistochemistry, using CD68 as a macrophage lineage marker, CD80 as a marker of pro-inflammatory macrophages, and CD163 as a marker of anti-inflammatory macrophages." (PMID 31481956, 2019). "Immunohistochemical staining was used to detect the macrophages infiltration (CD68 and CD163), epithelial–mesenchymal transition (EMT) markers (E-cadherin and Vimentin) expression in serial sections of human colorectal cancer (CRC) specimens." (PMID 30927925, 2019). "Colorectal cancer liver metastases (COAD-MET) were mostly CD8-excluded, corresponding to a CD68-excluded or CD68-hot phenotype." (PMID 30179157, 2018). "Immunohistochemistry for CD68 (macrophage marker), CD86 (M1 macrophage marker) and CD206 (M2 macrophage marker) was performed in biopsy samples from colorectal carcinoma resections." (PMID 24901518, 2014). "In addition, we verified significant positive expressions of CD68 (macrophage M0) and CD206 (macrophage M2) in 8 cases of colorectal cancer using immunohistochemistry and immunofluorescence techniques." (PMID 36611136, 2023).
colorectal cancer (continued). "Expressions of CD68, CD86 and CD163 were investigated by immunohistochemistry (IHC) and immunofluorescence (IF), and the correlation between the expression of CD86 and CD163 was calculated in colorectal cancer tissues from 64 CRC patients." (PMID 34964155, 2022). "Oppositely, for 208 patients resected for stage III colorectal cancer, high CD68+ TAMs in invasive front of tumor and in metastatic lymph node were associated with better DFS only in 5-fluorouracil-treated patients compared to untreated ones." (PMID 33194645, 2020). "CD68 was used as a marker of the presence of activated microglia in the cortex and three regions of the hippocampus (CA1, CA3, and dentate gyrus) in the BALB/c mice with colorectal carcinoma and C57BL/6J mice with lung carcinoma." (PMID 27893434, 2017). "Importantly, CD68 reached relatively high expression in advanced colorectal cancer patients and had negative correlation with their survival probability." (PMID 36774343, 2023). "However, amount of intramural CD68+TAMs showed negative correlation with the bad outcome in patients with colorectal cancer." (PMID 36686729, 2022). "The CD68 antigen, expressed by immature dendritic cells and macrophages that are ready to take up antigen, is included in our list of genes up-regulated in MSI-H colorectal cancer, as is the TLR-2 gene, one of a family of receptors to which HSP's bind to activate dendritic cells." (PMID 15298707, 2004). "Interestingly, in colorectal cancers (CRCs), CD163-positive M2-like macrophages exhibit anti-tumor activity in tumors with low levels of the anti-phagocytotic marker CD47 and positively correlate with the expression of CD68, which predicts increases in long-term survival." (PMID 38255296, 2024).
gastric cancer (59 papers, 2012 to 2025). A primary or metastatic malignant neoplasm involving the stomach. "In previous studies, SARIFA-positivity has been associated with increased macrophage (CD68+) infiltration at the invasive margin of gastric cancer." (PMID 40055484, 2025). "The increased density of CD163-positive TAMs, along with the high CD68 expression, was also associated with upregulated immune signaling and improved outcomes for gastric cancer." (PMID 38255296, 2024). "Association between the expression of VISTA and CD68 was also validated in gastric cancer patient cohort." (PMID 38356419, 2024). "Elevated levels of CD68-positive infiltrating TAMs in gastric cancer (GC) are associated with increased metastasis and poor prognostic outcomes." (PMID 39717759, 2024). "Similar studies revealed CD68+ TAMs were associated with poor survival in gastric cancer and hepatocellular carcinoma, respectively." (PMID 37397243, 2023). "The high infiltration of macrophages marked by CD68 in gastric cancer samples was significantly associated with the resistance of gastric cancer to chemotherapy." (PMID 36151545, 2022). "In gastric cancer, high infiltration of M2 macrophages was associated with poor prognosis, and high infiltration of CD68+ TAMs was associated with clinical stage and poor outcome." (PMID 33194593, 2020). "In gastric cancer, the clinical outcome was associated with high number of tumor‐associated macrophages (CD68+CD163+) and their proximity to tumor cells." (PMID 33072322, 2020). "CD8 and CD68 have been reported to be associated with the development and prognosis of gastric cancer." (PMID 30813210, 2019). "Additionally, the infiltration of CD163+, CD68+, and CD66b+ cells in gastric cancer tissue was significantly increased and independently associated with gastric cancer prognosis." (PMID 40387965, 2025). "Also, in an analysis of the expression of CD68+ macrophages in a series of 401 patients operated on for gastric cancer, another group found an association between CD68-positive tumors and shorter disease-free survival." (PMID 33194593, 2020). "Tumor-infiltrating CD8+ T cells and CD68+ TAMs in resected gastric cancer are predictive of the postoperative prognosis and benefits of adjuvant chemotherapy, whereas FOXP3+ T-cell infiltration is associated with worse outcomes." (PMID 39679910, 2025). "Meantime, the CD19 expression (B cell marker) was also decreased in gastric cancer, and CD68 (Macrophage marker) expression elevated in gastric cancer." (PMID 39712017, 2024). "Overall survival (OS) of patients with gastric cancer with low and high densities of cTOB1+, nTOB1+, CD66b+, cTOB1+CD66b+, nTOB1+CD66b+, CD68+, cTOB1+CD68+, and nTOB1+CD68+ cells was analyzed using Kaplan–Meier analysis." (PMID 38617839, 2024). "Our results also revealed that the density of CD68+ macrophages in gastric cancer tissue was greater than that in the corresponding paracancerous tissues, and the expression of cTOB1/nTOB1 in CD68+ macrophages followed the same pattern." (PMID 38617839, 2024). "Within the tumor microenvironment of gastric cancer, patients with high CD68+ macrophage expression have poorer prognosis." (PMID 38617839, 2024). "To investigate the biodistribution of macrophages in gastric cancer, we detected the expression of CD68, one of the markers of macrophages, in 103 clinical samples from patients receiving 5-FU based neoadjuvant chemotherapy by immunohistochemistry." (PMID 36151545, 2022). "In gastric cancer, macrophages with a CD68+CD163+CD206+ phenotype was found mainly located in stroma, and the CD68+IRF8+ macrophages were over-presented in the core region in comparison to the marginal zone." (PMID 35461288, 2022). "Clinicopathological features and CD169+/CD68+ ratio in lymph node sinus macrophages (LySMs) from 294 patients with gastric cancer." (PMID 33816277, 2021).
gastric cancer (continued). "The correlation between HMGB1 and CD68 has been observed in gastric cancer, but the correlation between HMGB1 and CD163 and CD33 has not been reported." (PMID 34257571, 2021). "Consistently, a significant positive correlation was found between the expression of CCL5 and CD68 in gastric cancer tissues." (PMID 34638423, 2021). "The prognostic significance of CD68-positive macrophages is still controversial in gastric cancer, and a larger sample size is needed to clarify its prognostic significance." (PMID 34458140, 2021). "In a very recent study on dMMR gastric cancer, CD68+CD163− M1-like macrophages were identified as prerequisites for efficient PD-L1/PD-1 blockade because of specific chemokine receptor expression likely activating CTL." (PMID 33870463, 2021). "For instance, in gastric cancer patients, the median value of CD68+NOS2+ (M1)/CD68+CD163+ (M2) ratio was found to be a positive independent predictor of survival." (PMID 34572013, 2021). "CD68 expression in gastric carcinomas was higher in the H. pylori-positive groups than in the H. pylori-negative group." (PMID 33376580, 2020). "In order to test for changes in TAM (CD68) expression after treatment, we first investigated the preservation of macrophages in their morphology and number in human gastric cancer slice cultures." (PMID 31413815, 2019). "On the other hand, our study found that the expression of B7-H4 in immune cells was positively correlated with the infiltration of CD68-positive cells during gastric cancer progression, but negatively related with the infiltration of CD8-positive cells." (PMID 30813210, 2019). "Overall, this meta-analysis reveal that although CD68+ TAMs infiltration has the neutral prognostic effects on OS, the M1/M2 polarization of TAMs are predicative factor of prognosis in gastric cancer patients." (PMID 28081243, 2017). "We examined the effect of CD68+, M1 and M2 TAMs on the overall survival of patients with gastric cancer." (PMID 28081243, 2017). "Gastric cancer tissues selected for double immunofluorescent staining showed wide infiltration of tumor-associated macrophages (TAM), which were characterized by CD68." (PMID 29156791, 2017). "In summary, our findings reveal that although CD68+ TAMs infiltration has the neutral prognostic effects on OS, the M1/M2 polarization of TAMs are predicative factor of prognosis in gastric cancer patients." (PMID 28081243, 2017). "Gastric cancers were scored as “0” or “1” in each area when the density of CD68+ and CD163+ TAMs was below or above the median value." (PMID 26714314, 2015). "Results showed a positive relationship with Bmi1 and CD68/CD163 expression in gastric cancer and in colon cancer." (PMID 24312366, 2013). "In endometrial cancer and gastric cancer, dense infiltration of CD68+ cells in the TN positively correlated with fewer recurrences and hence suggested a beneficial effect of TAMs in the TN." (PMID 22824040, 2012). "For example, the heterogeneity and distribution of TAMs in breast and gastric cancers were explored through fluorescence microimaging and a multiplex panel including markers like CD68, CD163, CD206, IRF8, and PDL1, identifying distinct TAM populations within tumor and adjacent tissues." (PMID 39068459, 2024). "Moreover, this study further highlights that patients with gastric cancer with an elevated density of cTOB1+CD68+ macrophages experience unfavorable prognoses (P = 0.024)." (PMID 38617839, 2024). "MxIF also verified the co‐expression of VISTA and CD68 in gastric cancer." (PMID 38356419, 2024). "Its expression level in CTSB+ and CD68 + macrophage could act as an indicator for early warning of primary gastric cancer." (PMID 36333291, 2022). "A recent study noted that the CD163+CD206− TAMs were associated with up-regulated immune signaling and improved survival in gastric cancer, whereas the infiltration of CD68+ only and CD163−CD206+ only TAMs was correlated with a high expression of PD-L1 and tumor immune escape." (PMID 36291863, 2022).